CRP (C-reactive protein)
Diseases named in the same sentence as CRP in open-access papers (continued):
Sharing a sentence is not in itself a finding about the gene and the disease.
Zinc deficiency (19 papers, 2010 to 2026). A deficiency of the essential metal Zinc; an essential cofactor for many enzymes. "As in our study, zinc deficiency was associated with the female sex, high CRP values, and low albumin levels." (PMID 41228451, 2025). "The authors of this study also controlled for markers of inflammation, including CRP and albumin, as we did in our study, emphasizing the independent impact of zinc deficiency on unfavorable clinical outcomes, particularly in CD." (PMID 41228451, 2025). "IBD-related complications were more common in patients with CD subtype (p = 0.041), perianal CD (p = 0.011), zinc deficiency (p < 0.001), high CRP (p < 0.001), high FCP (p = 0.026), and low albumin (p < 0.001)." (PMID 41228451, 2025). "Due to the granular data available on our cohort, we were able to attempt to control for markers inflammation including CRP and albumin while analyzing the impact of zinc deficiency on clinical outcomes." (PMID 41228451, 2025). "On the one hand, we found considerable inconsistency in the data, as a minority of 33% indicated a significant correlation between zinc deficiency and elevated CRP, while a statistical relation or data collection was lacking for the remainder." (PMID 36235709, 2022). "In order to supplement the biological explanation of our prevalence data, we looked at information on inflammation in the selected reports, considering CRP values and disease activity scores in relation to zinc deficiency." (PMID 36235709, 2022). "Survey-specific analyses of the prevalence of zinc deficiency according to CRP or AGP decile were generally consistent with the results of the correlation analyses." (PMID 32266402, 2020). "Adjustment methods that only used CRP often reduced the prevalence of zinc deficiency in PSC by a similar degree to methods that accounted for both CRP and AGP." (PMID 32266402, 2020). "The exclusion of observations with CRP concentrations > 5 mg/L resulted in a small decrease in the estimated prevalence of zinc deficiency, of 0.7–3.9 percentage points (pp)." (PMID 32266402, 2020). "In 6 of 12 PSC surveys, the estimated prevalence of zinc deficiency increased with increasing CRP deciles, and to a lesser extent, with increasing AGP deciles." (PMID 32266402, 2020). "Zinc deficiency also correlated with male gender (p < 0.001), low albumin (<3.5 g/dL) (p=0.001), and elevated CRP (≥0.5 mg/dL) (p=0.001)." (PMID 30405910, 2018). "Plasma concentrations of zinc and CRP were measured to determine zinc deficiency and the degree of inflammation in Malawian infants, and to investigate possible associations with season of birth and cytokine/chemokine signatures." (PMID 24708690, 2014). "Elevated CRP, advanced age, inferior maternal socioeconomic status, dependence on poorly-diversified and plant source-based diets, zinc deficiency, and history of too close and too many births were pertinent risk factors of VAD." (PMID 23930336, 2013). "Moreover, patients with zinc deficiency had significantly higher mean (SD) blood concentrations of CRP (2.9 mg/dL [4.2] vs. 1.2 mg/dL [2.6]; p < 0.01) than the control group." (PMID 40344157, 2025). "The median CRP was significantly higher in the zinc deficiency group (12.1 vs. 3.4, p < 0.001)." (PMID 41228451, 2025). "Interestingly, our study yielded similar results, indicating that patients with zinc deficiency had significantly higher mean (SD) blood concentrations of CRP (2.9 mg/dL [4.2] vs. 1.2 mg/dL [2.6]; p < 0.01) than the control group." (PMID 40344157, 2025). "Considering all the highlights, we should indicate that although the assessed biomarkers of inflammation (ESR and CRP) were normal, the high Cu/Zn ratio should alert us to a condition with a high inflammatory response and could reflect the severity of zinc deficiency." (PMID 33143143, 2020).
Zinc deficiency (continued). "No clear pattern could be identified between the prevalence of zinc deficiency and either CRP decile or AGP decile in the pooled analysis of the 5 WRA data sets that measured both CRP and AGP concentrations, and the same was true for most of the country-specific analyses." (PMID 32266402, 2020). "Overall, the application of any of the RC models including both CRP and AGP reduced the estimated prevalence of zinc deficiency by 4.1–18.2 pp." (PMID 32266402, 2020). "The relation between the estimated prevalence of zinc deficiency and CRP decile visually appeared to follow a positive linear pattern in the pooled analysis of the 6 PSC data sets that measured both CRP and AGP concentrations." (PMID 32266402, 2020). "In all 6 surveys, application of the RC approach, adjusting for both CRP and AGP when available, resulted in the largest reduction from the unadjusted prevalence of zinc deficiency; this reduction was consistently significant." (PMID 32266402, 2020). "Our pooled decile analysis of PSC data sets that measured both CRP and AGP revealed a clear positive linear association between the prevalence of zinc deficiency and CRP decile, and a generally higher prevalence of zinc deficiency among higher AGP deciles." (PMID 32266402, 2020). "The estimated prevalence of zinc deficiency decreased when ICFs for CRP only, AGP only, and both CRP and AGP were used to adjust the PZC across all 6 surveys." (PMID 32266402, 2020). "Children with zinc deficiency had higher median values of the neutrophil-to-lymphocyte ratio (NLR) (1.84 vs. 1.09, p = 0.0010), C-reactive protein (CRP) levels (9.65 vs. 3.96 mg/L, p = 0.0053), and fibrinogen levels (2.88 vs. 2.07 g/L, p = 0.0057) compared to those with adequate zinc levels." (PMID 40201587, 2025). "The magnitude of the reduction was comparable when exclusions were based only on AGP concentrations > 1 g/L. Excluding observations with elevated CRP or AGP concentrations resulted in the largest reduction in sample size; however, the change in the prevalence of zinc deficiency remained small." (PMID 32266402, 2020). "It is worth noting that the adjustment methods had the greatest impact on the prevalence of zinc deficiency among PSC in Cameroon, the country that demonstrated the highest unadjusted prevalence of zinc deficiency, highest mean CRP concentration, and among the highest mean AGP concentrations." (PMID 32266402, 2020). "The decision to apply adjustment methods should consider the strength and significance of the correlation coefficient between PZC and CRP or AGP, and should also include a visual inspection of the decile analysis to confirm an increasing prevalence of zinc deficiency by CRP or AGP decile." (PMID 32266402, 2020). "Therefore, both CRP and serum albumin have been reported to be associated with elevated CRP, IL-6, TNF-α, IL-1β, and zinc deficiency." (PMID 30941358, 2019). "Several previous studies have found that zinc deficiency in MHD patients may result in increased oxidative stress and CRP concentrations." (PMID 29457023, 2017). "In Malawi, a proportion of infants had zinc deficiency and elevated plasma CRP (>10 mg/L), but neither zinc deficiency nor high CRP was associated with production of any of the cytokines measured." (PMID 24708690, 2014). "However, multivariate logistic regression analysis revealed that CRP concentration was not a predictive factor for zinc deficiency." (PMID 40344157, 2025).
bronchitis (18 papers, 2013 to 2025). An acute or chronic inflammatory process affecting the bronchi. "In our multivariate models, the effect of bronchitis persisted after introducing preoperative CRP, a marker of systemic inflammation, underlining the negative predictive value of both systemic and local inflammation." (PMID 35205621, 2022). "Increasing C-reactive protein (CRP) levels by tenfold (OR = 5.14; 95% CI, 3.34–8.12; p < 0.001) or suspected chest infection on a radiograph (OR = 5.81; 95% CI, 3.23–10.89; p < 0.001) increased the OR of antibiotic treatment by fivefold." (PMID 40001364, 2025). "By that time, his chest infection was under control and his CRP had normalized." (PMID 38528249, 2024). "CRP values were reported significantly high in the purulent bronchitis." (PMID 23497669, 2013). "On admission, initial laboratory investigations revealed mildly elevated C-reactive protein (CRP) and white blood cell (WBC) count, which were already being addressed with oral co-amoxiclav for a suspected chest infection." (PMID 41393631, 2025). "Three of the intervention practices, A, D and G, performed more than 60% of the tests available and more than 30 CRP tests per 100 consultations with lower RTI, bronchitis, acute cough and chest infection, and were classified as high-fidelity practices." (PMID 33153517, 2020). "Overall CRP POCT uptake in the eight general practices ranged considerably dependent on number of consultations for 18–64-year-olds with lower RTI, bronchitis, acute cough and chest infection." (PMID 33153517, 2020).
Candidemia (18 papers, 2013 to 2025). A form of invasive candidiasis where species of CANDIDA are present in the blood. "Previous research has shown that older age, male sex, ALL, high levels of C-reactive protein, and the presence of candidemia were linked to worse clinical outcomes." (PMID 40806822, 2025). "Multivariate analysis identified hypoproteinemia, septic shock, and elevated CRP levels as independent risk factors for mortality in C. albicans candidemia." (PMID 41561091, 2025). "Third, lower levels of platelets, hemoglobin, lymphocytes, white blood cells, C-reactive protein, procalcitonin, and monocytes are negatively associated with the risk of candidemia." (PMID 39250466, 2024). "Serum CRP (AUC 0.756, 95% CI 0.625–0.879, P = 0.001) was also valuable in predicting the prognosis of C. albicans candidemia." (PMID 41561091, 2025). "Also, it was previously reported to be more predictive of candidemia than leukocytes, CRP, and procalcitonin." (PMID 38545189, 2024). "In addition, patients with candidemia had higher C-reactive protein, bilirubin, fasting glucose, blood urea nitrogen, and lactic acid levels." (PMID 34309570, 2021). "A higher CRP value has been found in bacteraemia, compared to candidemia cases." (PMID 29371558, 2017). "Like PCT and CRP, lymphocytes, WBC and monocytes were negatively correlated with candidemia in this study." (PMID 39250466, 2024). "In summary, the individual biomarkers of candidemia were BDG ≥ 200 pg/mL (p < 0.001), CRP ≥ 130 mg/L (p < 0.001), and PCT < 3 ng/L (p = 0.012); PSEP > 700 pg/mL was borderline discriminative (p = 0.091)." (PMID 35330311, 2022). "Further, PCT is considered superior to CRP, serum amyloid A (SAA) and Interleukin (IL)-6 in predicting candidemia." (PMID 29371558, 2017). "A multivariable model consisting of the three variables had better predictive ability (AUC-ROC = 0.88, p < 0.001), for candidemia diagnosis, as compared to that of PCT, CRP, and NLR, whose AUC-ROCs were all lower (0.81, p < 0.001, 0.78, p < 0.001, and 0.68, p = 0.015, respectively)." (PMID 38930085, 2024). "In comparison with mono-candidemia, patients with mixed C/B-BSIs had a higher glutamic-oxaloacetic transaminase (GOT), higher lactic acid and elevated inflammatory markers evidenced by significant increases in levels of procalcitonin and CRP (all P < 0.05)." (PMID 36320023, 2022). "In circumstances where one would anticipate very high CRP levels, such as cases of candidemia, no CRP was demonstrated bound to fungi, nor in any other case." (PMID 30227609, 2018). "Fourthly, although specific fungal serological markers are expensive, cheaper alternatives like PCT and CRP, which have shown a high negative predictive value may be standardized and validated for excluding candidemia." (PMID 29371558, 2017).
cardioembolic stroke (18 papers, 2014 to 2025). "Development of an HT after AIS was associated with admission NIHSS score, cardioembolic stroke, intravenous tPA treatment, and endovascular treatment, along with calprotectin and CRP in univariate analyses." (PMID 33402185, 2021). "We found that patients with cardioembolic strokes at baseline had higher levels of CRP, IL-6, and neopterin at 3 months, indicating a difference in the inflammatory profile between these subgroups." (PMID 34879833, 2021). "The mean values of CRP were significantly higher in patients with cardioembolic stroke compared with an atherothrombotic large vessel and lacunar stroke." (PMID 33050269, 2020). "Several studies reported that elevated levels of the inflammatory biomarkers, c-reactive protein (CRP), tumor necrosis factor-α (TNF-α), interleukin-6 (IL-6), interleukin-1β (IL-1β), are associated with cardioembolic stroke." (PMID 33050269, 2020). "For example, CRP was elevated in patients with atherothrombotic or cardioembolic stroke." (PMID 31242583, 2019). "For example, evidence suggests that inflammatory biomarkers like C-reactive protein (CRP), IL (interleukin)-6, IL-1b, TNF-a and D-dimer alongside cardiac biomarkers such as B-type natriuretic peptide (BNP) or its N-terminal fragment, NT-pro-BNP are all associated with cardioembolic stroke." (PMID 40117100, 2025). "A tendency towards slightly more elevated body temperatures, but not CRP or WBC, was seen among patients with cardioembolic strokes." (PMID 40447994, 2025).
gastrointestinal infections (18 papers, 2013 to 2026). "The increases of both ALAT and CRP might also point at moderate liver damage and inflammation due to environmental exposure, the latter causing mild gastrointestinal infections from drinking water from waterholes, and small injuries on the legs and arms inflicted by thorns and falls." (PMID 27366752, 2016). "Serum 25-hydroxyvitamin D levels, immune markers (total lymphocyte count, immunoglobulin levels, C-reactive protein, and erythrocyte sedimentation rate), and reported respiratory and gastrointestinal infections over the preceding six months were assessed." (PMID 41700250, 2026). "Secondary outcomes assessed respiratory and gastrointestinal infection incidence, inflammatory markers (C-reactive protein), and safety parameters." (PMID 41262831, 2025). "What is more, patients presenting with symptoms of a respiratory system infection as compared with patients presenting with symptoms concerning a digestive system infection have higher CRP levels including substantively more CRP levels above 100 mg/dL." (PMID 36649001, 2022). "Notably in a survey on pre-school children in Ghana, high doses of vitamin A- every 4 months for one year- elevated CRP in children with gastrointestinal infections with vomiting." (PMID 23983997, 2013). "The high values of CRP and ESR tests reported in group II indicate the occurrence of severe intestinal infections, this is due to the toxic effects of the ricin compound in castor oil." (PMID 39554354, 2024).
Hypernatremia (18 papers, 2014 to 2026). An abnormally increased sodium concentration in the blood. "The trend of the patient's sodium levels, along with the inflammatory marker CRP, showing the slow resolution of hypernatremia paralleling the control of infection, underscores this association." (PMID 41536631, 2026). "Biochemically, he exhibited elevated C-reactive protein (CRP) of 56 mg/L, creatinine of 129 μmol/L, an estimated glomerular filtration rate (eGFR) of 54 mL/min/1.73 m2 and marked hypernatremia of 153 mmol/L." (PMID 41341140, 2025). "Notably, the hypernatremia subgroup also showed a trend toward elevated serum CRP levels as compared with Q2-Q4 subgroups." (PMID 33552948, 2020). "Impaired consciousness was very strongly correlated with hypernatremia, with OR = 8.54, CI: 4.83–15.09, p = 0.0000, alongside SBP and CRP." (PMID 37109139, 2023). "In fact, the presence of E. coli leads to an increase of CRP, creatininemia, glycemia, LDL cholesterolemia, triglyceridemia, hyperkaliemia, and hypernatremia, and this is more accentuated in diabetic patients with unbalanced glucose levels." (PMID 36624799, 2022).
intestinal obstruction (18 papers, 2016 to 2025). Blockage of the normal flow of the intestinal contents within the bowel. "In this study, CRP was identified as an independent risk factor for intestinal obstruction (OR = 1.137, 95% CI: 1.038–1.245), indicating that each 1 mg/L increase in CRP is associated with a 13.7% higher risk of obstruction." (PMID 40823570, 2025). "CRP, a sensitive marker of the inflammatory response, plays a crucial role in the pathogenesis of radiation enteritis complicated with intestinal obstruction." (PMID 40823570, 2025). "Correlation analysis of Fib, CRP, NEUT, and TT between the simple intestinal obstruction group and the strangulated intestinal obstruction group showed that Fib and CRP were significantly correlated with all forms of intestinal obstruction (r=0.63, P<0.01)." (PMID 34292211, 2021). "As infection often occurs from simple intestinal obstruction to strangulated intestinal obstruction, our data also showed that inflammatory markers like CRP and NEUT also increased." (PMID 34292211, 2021). "In summary, Fib and CRP showed a good ability to distinguish between strangulated intestinal obstruction and simple intestinal obstruction." (PMID 34292211, 2021). "Clinically, significant correlations between elevated serum IL-6 levels and other clinical factors such as serum CEA, CRP, and bowel obstruction have been previously reported." (PMID 26858756, 2016). "When no bowel resection was needed for the surgical repair of bowel obstruction, 7 perioperative factors including male sex and elevated baseline as well as postoperative CRP levels were significantly associated with POI." (PMID 40889024, 2025). "Meanwhile, Li found that CRP level was able to reflect the inflammatory condition of strangulated intestinal obstruction with necrosis and showed a good ability to distinguish between strangulated intestinal obstruction and simple intestinal obstruction." (PMID 35795333, 2022). "Therefore, CRP and Fib have a greater value in the diagnosis of strangulated intestinal obstruction." (PMID 34292211, 2021). "Levels of fibrinogen (Fib), C-reactive protein (CRP), neutrophil ratio, and D-Dimer were significantly greater, while thrombin time was significantly shorter in strangulated intestinal obstruction compared with simple intestinal obstruction." (PMID 34292211, 2021). "Fib and CRP have high specificity and positive predictive value, indicating that both of them have a certain significance for intestinal strangulation in patients with intestinal obstruction (but other factors affecting coagulation must be excluded)." (PMID 34292211, 2021). "In the setting of emergency surgery, preoperative CRP was associated with a higher incidence of difficult cholecystectomies and perforated appendicitis, but its role in predicting the outcomes after surgery for bowel obstruction has not yet been reported." (PMID 39452550, 2024). "In particular, the CRP level was significantly different between the simple intestinal obstruction group and the strangulated intestinal obstruction group (P<0.01), as well as the ischemic subgroup and the necrosis subgroup of the patients with strangulated intestinal obstruction (P<0.01)." (PMID 34292211, 2021). "The elevated C-reactive protein (CRP) and procalcitonin levels indicated an inflammatory response, possibly secondary to bowel obstruction." (PMID 39748813, 2024). "The values of Fib, CRP, NEUT, and D-D were significantly greater in the strangulated intestinal obstruction group than in the simple intestinal obstruction group (P<0.01)." (PMID 34292211, 2021). "Using the cutoff values, the sensitivity, specificity, positive predictive value, and negative predictive value for Fib and CRP in discriminating between strangulated intestinal obstruction and simple intestinal obstruction were determined." (PMID 34292211, 2021).